TNF (tumor necrosis factor)
Diseases named in the same sentence as TNF in open-access papers (continued):
Sharing a sentence is not in itself a finding about the gene and the disease.
Peri-Implantitis (continued). "In conclusion, our study demonstrates that after three months of therapy, there was a significant reduction in the expression of cytokines in the peri-implant crevicular fluid of patients with peri-implant mucositis (IL-17A and TNF-α) and peri-implantitis (IL -1β, IL-6, and TNF-α)." (PMID 39860346, 2025). "Logistic regression analysis revealed that smoking, PI, and probing depth were significant predictors of peri-implantitis, while IL-10 and TNF-α exhibited a positive and slight negative association, respectively." (PMID 40959363, 2025). "Peri-implantitis is characterized by chronic inflammation around dental implants driven by bacterial plaque accumulation, which triggers an immune cascade involving proinflammatory cytokines, such as IL-6 and TNF-α, to combat infection and tissue damage." (PMID 40959363, 2025). "A study investigating the relationship between miRNA-27a and peri-implantitis in dogs showed that an increase in miRNA-27a might induce osteogenesis by reducing TNF-α." (PMID 38610701, 2024). "In peri-implantitis, TNF-α, IL-1α, and IL-6 are significantly upregulated." (PMID 36768829, 2023). "The balance of RANKL/OPG in peri-implantitis is influenced by TNFα and NFkB in favor of RANKL." (PMID 37232785, 2023). "Additionally, cytokines of IL-15, TNF-α, and IL-1α showed comparable amounts between healthy implants and peri-implantitis (p < 0.05)." (PMID 36233685, 2022). "Previous studies revealed that TNF-α level was significantly higher in PISF from peri-implantitis sites than that in healthy peri-implant tissue, indicating that TNF-α may be involved in the development of peri-implant disease." (PMID 34610045, 2021). "Certain cytokine inhibitors such as TNF-α antagonists and IL-1 receptor antagonists have exhibited anti-inflammatory effects in periodontal diseases and may be used for treating peri-implantitis." (PMID 34931168, 2021). "Thus, IL-1 and TNFα, two crucial pro-inflammatory cytokines mediating the inflammation process of peri-implantitis, are potential predictive markers for development of peri-implant disease." (PMID 34610045, 2021). "High amounts of TNF-α have been found in regions with peri-implantitis and periodontitis." (PMID 33376734, 2020). "The most used biomarkers to assist the early diagnosis of peri-implantitis are IL-1β and TNF-α." (PMID 33111201, 2020). "In their recent experimental peri-implantitis study in mice, high expression levels of TNFα and IL1 were observed during the first 2 weeks after application of plaque accumulating 5-0 silk-ligatures, followed by a subsequent decrease back to baseline levels after 4 weeks." (PMID 31426572, 2019). "Both IL-1β and TNF-α are important mediators of the pathogenesis of peri-implantitis." (PMID 28864780, 2017). "Therefore, it is of interest to evaluate the diagnostic efficacy of salivary biomarkers-interleukin-1β (IL-1β), matrix metalloproteinase-8 (MMP-8) and tumour necrosis factor-alpha (TNF-α)-by comparing their concentrations in patients with healthy peri-implant tissues and those with peri-implantitis." (PMID 41907937, 2025). "The study revealed that, concerning inflammatory factors, IL-12 and TNF-α were higher in severe peri-implantitis, followed by initial peri-implantitis and mucositis, while IL-4 was higher in healthy projects, followed by mucositis, severe, and initial peri-implantitis." (PMID 35846759, 2022). "Furthermore, the significantly higher levels of TNFα in peri-implantitis patients indicated that TNFα also played a key role in peri-implantitis and that TNFα was a proinflammatory cytokine that promoted the resorption of the bone and mediates the infection's inflammatory response." (PMID 35292688, 2022). "Another two systemic reviews presented that pro-inflammatory cytokines in PICF, such as IL-1β, TNF, and IL-6, were significantly elevated in peri-implantitis and could be used as adjunct tools to clinical parameters to differentiate healthy implants from peri-implantitis." (PMID 36233685, 2022).
Peri-Implantitis (continued). "Although the present study was the first to assess the TNF-α, IL-10, VEGF, and HIF1-α immune balance in peri-implantitis, it has limitations since we evaluated the local immune response of the peri-implant condition at a given time." (PMID 38477721, 2024). "Among DM patients with peri-implantitis, adjunctive ICG-PDT and MB-PDT demonstrated comparable outcomes in terms of peri implant clinical and pro-inflammatory characteristics (IL-6 and TNF-α) than MD alone." (PMID 39882195, 2024). "This study, for the first time demonstrates the balance of HIF-1α, TNFα, IL-10, and VEGF in peri-implantitis." (PMID 38477721, 2024). "In peri-implantitis, access flap debridement alone can significantly reduce some investigated biomarkers (MMP-8 and TNF-a) in the long-term (12 months after surgery)." (PMID 36360962, 2022). "This eventually activates the transcription factor NF-κB, which regulates a large range of cytokines, including IL-1β, TNF-α, and RANKL/OPG; many of them have been shown to play a pathologic role in peri-implantitis." (PMID 34401982, 2021). "The expression levels of other pro-inflammatory factors, such as IL-1β, Il-6, IL-8, and TNF-α, were also higher in the GCF from peri-implantitis sites than in the GCF from healthy sites." (PMID 32760399, 2020). "The presence of herpesviruses in patients with peri-implantitis suggests the development of a proinflammatory environment, which is characterized by increased expression of MIP-1β and TNF-α in saliva." (PMID 30158834, 2018). "Our Endocan findings contrast markedly with traditional inflammatory mediators, where Unlike IL-1β and TNF-α which typically elevate in both mucositis and peri-implantitis (Dursun and Tözüm, 2016), Endocan demonstrated specificity for peri-implantitis only." (PMID 40739222, 2025). "This study investigated the roles of interleukin-6 (IL-6), interleukin-10 (IL-10), and tumor necrosis factor-alpha (TNF-α) in peri-implantitis by comparing their levels in peri-implant crevicular fluid (PICF) between healthy implants and peri-implantitis groups." (PMID 40959363, 2025). "This was the first study to correlate TNF-α and VEGF in the peri-implantitis." (PMID 38477721, 2024). "Furthermore, the positive correlation between TNF-α and VEGF suggests intensified proinflammatory activity in peri-implantitis." (PMID 38477721, 2024). "This study aimed to compare the levels of HIF1-α, VEGF, TNF-α, and IL-10 in the peri-implant crevicular fluid of patients with and without peri-implantitis." (PMID 38477721, 2024). "The authors compared the levels of HIF1-α, VEGF, TNF-α, and IL-10 in peri-implant crevicular fluid between patients with or without peri-implantitis." (PMID 38477721, 2024). "However, it is crucial to acknowledge that this study represents the first attempt to correlate TNF-α, IL-10, VEGF, and HIF1-α in peri-implantitis." (PMID 38477721, 2024). "Considering these findings, we hypothesized peri-implantitis increases the expression of VEGF, HIF-1α, TNF-α, and IL-10 in the PICF." (PMID 38477721, 2024). "Furthermore, the simultaneous increase in TNF-α and VEGF was identified as a potential contributor to the heightened inflammatory response in peri-implantitis, a response that appeared to be counterbalanced by the elevated levels of IL-10." (PMID 38477721, 2024). "The level of chemical mediators, such as interleukin (IL)-1β, tumor necrosis factor (TNF)-α, and calprotectin, in peri-implant crevicular fluid (PICF) correlates with the progression of peri-implantitis and its usefulness as a biomarker of peri-implant disease is becoming clear." (PMID 36834667, 2023). "Other studies debate that TNFα (+308) does not always present an effect on peri-implantitis and needs other factors, such as smoking, to potentiate the TNFα (+308) genotype." (PMID 37232785, 2023). "Moreover, IL-1β and TNF-α were significantly higher in CVD patients, which were significant markers for peri-implantitis." (PMID 37745126, 2023).
Peri-Implantitis (continued). "IL-1β (p < 0.01), IL-6 (p < 0.01), IL-10 (p < 0.05) and TNF-α (p < 0.01) are significantly higher at the sites with peri-implantitis compared to healthy peri-implant tissue, while IL-8 did not increase significantly." (PMID 25888355, 2015). "In this study, it was found that IL-1β (p < 0.01), IL-6 (p < 0.01), IL-10 (p < 0.05) and TNF-α (p < 0.01) were significantly increased at the sites with peri-implantitis, while IL-8 was not." (PMID 25888355, 2015). "The qualitative evidence indicates that certain polymorphisms—particularly in the CD14, TNFα, IL-1, and EGF genes—show consistent associations with increased susceptibility to peri-implantitis, while others (e.g., MMP13, TGFB3, RANKL) demonstrate no clear relationships." (PMID 41373620, 2025). "During the treatment of peri-implant mucositis and peri-implantitis there were minimal effects of non-surgical treatment alone on the investigated inflammatory biomarkers (IL-4, IL-10, and IL-12, TNF-a, RANKL, OPG IL-1β, IL-6, TNF-α, MCP-1/CCL2, MIP-1α/CCL3, IFN-γ, MMP-8, sRANKL, OPG and G-CSF)." (PMID 36360962, 2022). "This study evaluated the presence of cytokines (IL-1β, IL-2, IL-4, IL-6, MCP-1, MIP-1α, MIP-1β, and TNF-α) and human herpesvirus (HSV1, HSV2, EBV, CMV, VZV, HHV6, HHV7, and HHV8) in saliva samples taken from subjects with and without peri-implantitis." (PMID 30158834, 2018). "TNF-α revealed significant positive correlations with IL-10 (p=0.0008) and VEGF (p=0.0246), whereas HIF-1α and IL-10 levels (p=0.0041) demonstrated a negative and significative correlation in the peri-implantitis group." (PMID 38477721, 2024).
skin cancer (77 papers, 2010 to 2026). "TNF‐α deficient mice are more immunized to skin cancer cells, which provides evidence to support that TNF exerts a positive driving force on tumorigenesis." (PMID 40968783, 2026). "TNFα inhibitors are the most extensively studied biologic agents in the context of skin cancer risk." (PMID 40427207, 2025). "Studies have shown that patients with immunomodulator and anti-TNF use increase the risk of malignancy, especially skin cancers." (PMID 40933968, 2025). "Skin cancer resulted in a 3.23- and 3.67-fold increase in gene expression of NFκB and TNF-α associated with a 2.89-fold elevation in the skin levels of TNF-α as compared with control rats." (PMID 37284388, 2023). "Anti-tumor necrosis factor agents have been linked to opportunistic skin infections, psoriasiform lesions, and a potentially increased risk for skin cancer." (PMID 32842528, 2020). "Stigmasterol suppresses skin cancer by increasing the lipid peroxide levels and causing DNA damage and inhibits the development of cholangiocarcinoma via the downregulation of TNF-alpha and VEGFR-2." (PMID 32481565, 2020). "Allelic variants of TNF-α gene have been reported to contribute to the risk of skin cancer in certain populations." (PMID 28881857, 2017). "The TNFα deficient mice are resistant to the skin cancer development induced by UVR and DMBA-TPA tumor promotion protocol." (PMID 26918454, 2016). "Either TNF-α or TNF-α receptors deficient mice have reduced susceptibility to chemically induced skin cancers and develop fewer experimental metastases." (PMID 20087353, 2010). "This duality of TNFα may help explain the anti-inflammatory efficacy of anti-TNF agents, alongside their potential association with an increased risk of skin cancer and other malignancies." (PMID 40427207, 2025). "However, using transgenic mice with genetic deletion of TNF-α is linked to the protection of mice against ultraviolet radiation-induced skin cancer." (PMID 37284388, 2023). "For example, tumor necrosis factor-alpha-deficient mice are resistant to skin tumor development." (PMID 34248943, 2021). "Therefore, in this study, we carried out a comprehensive systematic review and meta-analysis to determine the association of TNF-α polymorphisms and the risk of skin cancer and different SCC diseases." (PMID 28881857, 2017). "Mice deficient of TNF or IL6 are more resistant to DMBA/TPA-induced skin tumor formation." (PMID 28467300, 2017). "However, the role of TNF-α polymorphisms in skin cancer is still inconclusive." (PMID 28881857, 2017). "Additionally, the long term risk of developing skin cancer reported in adults on anti-TNF treatment needs to be kept in mind especially in this case since patients with RDEB are more prone to epithelial squamous cell carcinomas; hence closed surveillance with regular skin examination is required." (PMID 21707991, 2011). "Given the association of RA with DLBCL and the increased risk of both secondary skin cancer and Richter's transformation in CLL/SLL, caution is warranted when considering TNF-alpha inhibitors in these patients." (PMID 40893576, 2025). "In a previous investigation of chemical carcinogenesis in a mouse skin cancer model we noted a TNF‐α‐dependent recruitment of innate immune cells to the skin during the initiation phase." (PMID 39288297, 2024). "In conclusion, 1,000 μg/ml of ethanolic extract had the lowest TNF-α concentration (187.67 pg/ml) as compared with other extracts in the case of skin cancer cell lines." (PMID 39687882, 2024). "Treatment of skin cancer mice with crocin significantly reduced the expression of NFκB and TNF-α in the skin samples from skin cancer mice." (PMID 37284388, 2023). "Signal transduction and transcriptional activator 3 signaling is significantly elevated in keratinocytes in psoriatic lesions, and TNF-α has been shown to be critical for skin canceration." (PMID 37503344, 2023).
skin cancer (continued). "Crocin produced therapeutic effects against skin cancer induced in mice by blocking the expression of Wnt followed by blocking the pro-inflammatory pathway through downregulation of NFκB and TNF-α." (PMID 37284388, 2023). "Caffeic acid, another phenolic compound, reduced the migration of skin cancer cells by regulation of p38, and quercetin decreased the production of TNF-α in obese rats, presenting an anti-inflammatory effect." (PMID 36555275, 2022). "Fisetin has significant effect on production of free fatty acids, tumor incidence, IL‐1α, TNF‐α, and antioxidant enzymes (glutathione and catalase contents) in ultravoilet‐induced skin cancer rats." (PMID 33473265, 2021). "TNF-α-antagonist-induced skin lesions include adverse mucocutaneous reactions, infectious complications, and skin cancers." (PMID 33477990, 2021). "The increased incidence of skin cancers in patients treated with anti-TNF-α agents is still controversial." (PMID 33477990, 2021). "Administration of anti-TNF monoclonal antibodies enhanced the resistance of mice to chemically induced skin cancer." (PMID 33917839, 2021). "Although keratinocyte-derived TNF plays a dominant role in other disease settings, this does not seem to be the case in the current context of carcinogen-induced skin tumor formation." (PMID 33497366, 2021). "TNFα signals to both tumor cells and their surrounding stromal cells during skin cancer development." (PMID 31051015, 2016). "One of the first studies demonstrating the importance of inflammation in skin cancer pointed to a tumor-promoting role of TNFα." (PMID 31051015, 2016). "Using TNF knockout mice the development of skin carcinomas by chemical carcinogen DMBA (7.12-dimethylbanz[a]-antracene) and tumor promoter TPA (12-0-tetradecanoyl-phorbol-13-acetate) decreased compared to wild type mice." (PMID 27389279, 2016). "Consistent with the pro-tumorigenic role of TNFα in the skin, administration of a TNFα-neutralizing antibody to mice significantly reduced skin tumor development." (PMID 31051015, 2016). "It has also been observed that TNF-α knockout (KO) mice were more resistant to chemical carcinogenesis of skin tumors." (PMID 25548907, 2014). "The role of TNF-α in tumor promotion is supported by the TNF-α-deficient mouse model, in which TNF-α−/− mice are resistant to the development of benign and malignant skin tumors." (PMID 23028877, 2012). "In TNF-α-deficient mice, okadaic acid has reduced tumour-promoting activity and the development of TPA-induced skin cancer is delayed." (PMID 20087353, 2010). "Finally, we found that treatment of skin cancer mice with crocin blocked the expression of NF-κB and TNF-α." (PMID 37284388, 2023). "With long-term monitoring of TNF-α and other tumor-associated markers, we suggest that the mechanism by which M2 macrophages affect tumor development and progression and the efficacy of PRP in skin cancer can be explored." (PMID 34193023, 2021). "The decreased expression of TNF-α and NF-κB triggered by cannabinoids noted in in vitro studies was also demonstrated in an in vivo study on the CB receptors in the inflammatory milieu of skin cancer." (PMID 34072930, 2021). "Additionally, TNFα KO and TNFα receptor KO mice are resistant to development of skin cancer elicited by repeated UVR exposure." (PMID 26918454, 2016). "TNFα has been reported an endogenous mouse skin tumor promoter." (PMID 26918454, 2016). "Additionally, mice deficient in TNF receptor type 1 (TNFR-1) and TNF receptor type 2 (TNFR-2) were resistant to the development of skin tumors, and knockdown of TNF-α in ovarian cancer cell lines led to diminished growth and vascular density." (PMID 25548907, 2014). "On the other hand, if it has a pro-tumor function, pharmacological inhibitors of the p38 MAPK pathway could be useful in reducing TNFα levels to eradicate skin tumors." (PMID 23965971, 2013).